INS (insulin)
Diseases named in the same sentence as INS in open-access papers (continued):
Sharing a sentence is not in itself a finding about the gene and the disease.
Hypoglycemia (continued). "TIR is usually applied in continuous glucose monitoring systems (CGMS), indicated in Germany only for patients with T1DM or T2DM on intensified insulin therapy or continuous subcutaneous insulin infusion at risk of severe hypoglycemia." (PMID 34449695, 2021). "Dosing insulin at bedtime and sulfonylurea in the day is a widely accepted regimen that can help to reduce the risk of hypoglycemia." (PMID 34165382, 2021). "This closed loop algorithm tries to reduce the risk of hypoglycemia raising the glycemic target when the patient’s glycemia increases, making the controller’s response slower and being conservative in terms of insulin usage." (PMID 34372462, 2021). "Provided the β-cells are fully functional, sulphonylureas, such as glibenclamide, can cause hypoglycemia since insulin release is initiated even when glucose concentration is below the normal threshold due to glucose-stimulated insulin release." (PMID 35003299, 2021). "The risk of overall confirmed hypoglycemia in the once-daily IDegAsp group was similar to that in the once-daily basal insulin group (OR 1.23, 95% CI 0.99 to 1.54, I2 = 0%)." (PMID 34564455, 2021). "Intramuscular administration of insulin leads to poor glycemic control and higher risk of hypoglycemia because of the extreme variability in insulin absorption through muscles (especially into exercising muscles)." (PMID 33492465, 2021). "The reduction in BG that is caused by insulin or any other form of drugs is known as iatrogenic hypoglycemia." (PMID 33466659, 2021). "Insulin-induced hypoglycemia causes AVP release into the circulation both in animals and in human subjects." (PMID 34867449, 2021). "In burned patients, this drug is as effective as insulin in lowering the plasmatic glucose levels and rarely causes hypoglycemia." (PMID 34068151, 2021). "This can become increasingly challenging with tightening glycemic control using insulin treatment, which increases the risk of hypoglycaemia." (PMID 34975743, 2021). "An insulin drug product with these characteristics would allow for rapid management of meal‐time glucose spikes and reduced risk of post‐prandial hypoglycemia." (PMID 34499434, 2021). "Potentially prandial bolus insulin associated hypoglycemia (+3 hrs of last dosing) accounted for 17% of all hypoglycemic episodes in both groups." (PMID 34295305, 2021). "For example, dose titration of insulin using FDA approved dose titration apps allows glycemic control to be achieved faster with lower risk of hypoglycemia induced by patient-led modulation of insulin doses." (PMID 34713185, 2021). "A frequently encountered problem in health care centers is the lack of access to diagnostic procedures such as ACTH stimulation tests or insulin-induced hypoglycemia tests." (PMID 33801854, 2021). "Group 1: Patients who use antidiabetic drugs prone to cause hypoglycemia alone (glimepiride, gliclazide, insulin)." (PMID 33750456, 2021). "The risk of overall confirmed hypoglycemia was similar between treatments; however, the risk of nocturnal hypoglycemia events was significantly lower with IDegAsp than with conventional premixed insulin and basal insulin." (PMID 34564455, 2021). "For patients initiating insulin who are currently taking a sulfonylurea (SU), the recommended best practice is to stop SU treatment to avoid risk of hypoglycemia." (PMID 33098260, 2021). "The association between lower C-peptide levels and CVD was significant after adjustment for clinical and demographic risk factors, baseline insulin and sulphonylureas use, and after adjustment for severe hypoglycemia or visit-to-visit glucose CV." (PMID 34879878, 2021). "An artificial pancreas requires that T1D patients adjust the insulin that is administered according to their diet, and there is a risk of hypoglycaemia if the patients accidentally administer more insulin than necessary." (PMID 34202521, 2021).
Hypoglycemia (continued). "Insulin dosing is recommended to be reduced by 50% to reduce the risk of hypoglycemia among patients with kidney disease; however, it should be continued until the resolution of ketoacidosis while maintaining euglycemia (BG: 140 – 180 mg/dL)." (PMID 36994324, 2021). "Inappropriate insulin secretion under low plasma glucose levels can cause severe and persistent hypoglycemia in newborns and children, leading to hyperinsulinemic hypoglycemia (HH)." (PMID 34777568, 2021). "The literature reports rare cases of monoclonal gammapathy of undetermined significance (MGUS) and multiple myeloma associated with the presence of anti‐insulin antibodies, causing hypoglycemia." (PMID 35844707, 2021). "The supporters of these low-carbohydrate diets argue that lower dietary carbohydrate intake eliminates postprandial hyperglycemia, decreases glycemic variability and through lower insulin dose decreases the risk of hypoglycemia." (PMID 34836158, 2021). "Insulinoma is a rare neuroendocrine tumor that causes excessive release of insulin, resulting in episodes of hypoglycemia." (PMID 34899593, 2021). "When insulin therapy is required to treat T2D, basal insulin (BI) is the preferred initial approach, because it allows similar glycemic improvement as compared with more intensive regimens, but with lower hypoglycemia risk." (PMID 34774054, 2021). "An automated insulin suspension allows the SAP to suspend insulin delivery when the CGM detects an unexpectedly low glucose level or risk of hypoglycemia." (PMID 33759789, 2021). "Newer and longer-acting second-generation analogs (insulin glargine 300 units/mL and insulin degludec) have been shown to lower the hypoglycemia risk compared to insulin glargine 100 units/mL." (PMID 34165382, 2021). "Overall, the most likely causes of hypoglycemia were due to carbohydrate deficit, by a cause secondary to acute illness or related to insulin therapy." (PMID 33402217, 2021). "Treatment options at this time are limited to exogenous insulin; although progress has been made in the precision of delivery of insulin and blood glucose monitoring, patients are at risk for life-threatening hypoglycemia." (PMID 33776933, 2021). "Vice versa, aggressive glucose lowering therapy in hospitalized patients, in particular using insulin with the risk of causing hypoglycaemia has also shown to negatively impact mortality." (PMID 34065762, 2021). "Additional in vivo studies showed that V1bR-mediated stimulation of glucagon secretion plays an important role in the counterregulatory hyperglucagonemia triggered by insulin-induced hypoglycemia or glucopenic conditions (deficiency of intracellular glucose)." (PMID 34752420, 2021). "Multiple animal and human studies have shown that administration of GLP-1RA can enhance β-cell recovery, reduce insulin dosage, reduce HbA1c content in the blood, reduce the risk of hypoglycemia and reduce inflammation." (PMID 33574570, 2021). "Our previous study of insulin therapy in T2D supports that the occurrence of hypoglycemia plays an independent role in the risk of developing CVDs in this population." (PMID 33602950, 2021). "Loss of consciousness due to hypoglycemia occurs almost exclusively in older, long-term diabetic patients, especially in combination with antidiabetic medication such as sulfonylurea or insulin." (PMID 33952305, 2021). "The promising so-called ‘smart insulin’ or glucose-responsive insulin that would reduce the risk of hypoglycaemia associated with insulin’s use is one innovation that is currently in the pipeline." (PMID 33483763, 2021). "Anti-diabetic medications like insulin or other OHAs were suggested to be discontinued to minimize the risk of hypoglycemia in this situation." (PMID 34496858, 2021). "The insulin sensitizers, biguanides and thiazolidinediones, and the inhibitors of α-glycosidase are associated with low risk of hypoglycemia." (PMID 34307650, 2021).
Hypoglycemia (continued). "A lower prevalence of severe hypoglycemia and a decline in total insulin units during pregnancy were associated with increased endogenous insulin secretion." (PMID 34959363, 2021). "It is noteworthy that the increased risk of hypoglycemia after insulin administration combines with fluoxetine." (PMID 34408704, 2021). "All six individuals were at “very high risk of hypoglycemia” due to risk factors like kidney disease, stroke, swallow palsy, diarrhea, insulin treatment (n = 5), and combination of insulin and sulfonylurea (n = 1) in addition to polypharmacy (n = 6)." (PMID 33407924, 2021). "As a matter of fact, in T1DM and advanced T2DM, there is a profound anatomic and functional derangement of intra-islet relationships between α and β cells, inducing the loss of cross-talking signals such as intra-islet insulin decrease during hypoglycemia." (PMID 34572493, 2021). "The main cause of hypoglycemia is the reduction in blood glucose levels because of an overdose of insulin or a low intake of food/carbohydrates." (PMID 33466659, 2021). "It is however challenging to achieve physiological glucose control for various limitations of intensive insulin therapy regimens, with the risk of hypoglycemia recognized as a major hurdle." (PMID 34054721, 2021). "On the contrary, an intermediate action NPH, a basal component of premixed insulin, shows peak activity 5–8 h after injection and demonstrates a high risk for hypoglycemia." (PMID 34564455, 2021). "Injection of insulin into different sites of the body was associated with an increase in insulin absorption, hyperinsulinemia and hypoglycemia in combination with physical activity." (PMID 34299312, 2021). "Hypoglycemia is a major complication of insulin therapy, causing approximately 100,000 emergency room admissions per year in the USA." (PMID 33564529, 2021). "A lower prevalence of severe hypoglycemia and a decline in required total insulin units during pregnancy were associated with increased endogenous insulin secretion." (PMID 34959363, 2021). "Whereas, several studies showed that flexible intensive insulin therapy improved glycemic control and decreased the risk of severe hypoglycemia." (PMID 34909088, 2021). "Over a mean follow-up of 2.3 years, the NNT using a GLP-1RA versus insulin to prevent one case of all-cause mortality and hospitalized hypoglycemia was 57 and 30, respectively." (PMID 33468131, 2021). "These latter observations provide an argument for routine utilization of relatively non-invasive CSGM, perhaps even with telemetry 22, in insulin-treated and other at-risk inpatients so that imminent hypoglycemia can be identified and circumvented." (PMID 34790048, 2021). "Insulin glargine is a long-acting insulin analog made using recombinant DNA technology, with greater predictability, and causes fewer hypoglycemia episodes, especially at night." (PMID 34917025, 2021). "Concurrently, it transiently doubles the risk of severe hypoglycemia as patientsbegin to take their newly prescribed medications, nearly all of which in this study wereassociated with heightened hypoglycemia risk (ie, insulin and sulfonylurea)." (PMID 34673968, 2021). "Glucose should be monitored before the start of the exercise session; adequate caloric supplementation is important to minimize the hypoglycemia risk before, during and after exercise depending on the insulin analogs utilized." (PMID 33870263, 2021). "RPG reduces the risk of hypoglycemia by stimulating insulin secretion only when blood glucose levels are higher than normal, whereas sulfonylureas induce insulin secretion even at low blood glucose levels." (PMID 34071139, 2021). "Her vomiting, fasting state, and continued use of insulin contributed to glycogen storage depletion causing euglycemia and even mild hypoglycemia." (PMID 34437030, 2021).
Hypoglycemia (continued). "There were significantly lower prevalence of neonatal hypoglycemia (risk difference (RD) − 0.07; 95%CI − 0.11, − 0.02) and preeclampsia (RD − 0.03; 95%CI − 0.06, 0) in the metformin group than in the insulin group." (PMID 34641848, 2021). "Recently, it has been shown that patients at risk of hypoglycemia had improved time in therapeutic range with insulin degludec 100 units/mL compared to glargine 100 units/mL." (PMID 34165382, 2021). "VGLUT2 deficient mice in SF1 neurons also had defective CRR to insulin-induced hypoglycemia and central 2-deoxyglucose, as this greater degree of hypoglycemia again linked to an impaired glucagon response." (PMID 34201257, 2021). "The causes of hypoglycemia also include age, insulin, weight loss, renal function decline, and changes in diet or drugs." (PMID 34925792, 2021). "The induction of insulin release only in the presence of high glucose (thus avoiding the risk of hypoglycaemia) and modulation of the early phase of insulin secretion account for the increasing use of GLP-1 mimetics in the treatment of type 2 diabetes (T2D)." (PMID 33658023, 2021). "Although methods for calculating additional insulin for HF/HP meals have been developed (e.g., Pankowska equation and Food Insulin Index), they are impractical in daily use or offer a higher risk of hypoglycaemia." (PMID 34684559, 2021). "Further, with shorter duration of insulin action, the risk of hypoglycemia, as a result of insulin stacking would be reduced." (PMID 34499434, 2021). "A post-hoc analysis of pooled data from the two Leuven studies further confirmed that TGC carried a significantly higher risk of hypoglycemia (which occurred in 11.3% of patients on TGC vs. 1.8% of those on conventional insulin therapy, p < 0.0001)." (PMID 33973089, 2021). "In agreement with previous studies, PAD caused fasting hypoglycemia and decreased plasma insulin level in ducks in the present study, indicating abnormal glucose metabolism." (PMID 34193047, 2021). "Sulfonylurea is generally tapered as the insulin dose increases, in order to reduce hypoglycemia risk." (PMID 34165382, 2021). "During rewarming, there is increased responsiveness to insulin and increased glucose consumption, leading to a higher risk of hypoglycemia." (PMID 34247627, 2021). "Our study disclosed that the use of insulin was associated with a significantly higher risk of severe hypoglycemia in persons with compensated cirrhosis compared with oral antidiabetic agents." (PMID 34118892, 2021). "Managing physical activity can be challenging primarily due to increased hypoglycaemia risk and altered insulin sensitivity." (PMID 33550442, 2021). "Artesunate and other artemisinins have been shown to cause hypoglycaemia, increased glucose-6-phosphate dehydrogenase activity, as well as the conversion of pancreatic α-cells to insulin-secreting β-like cells." (PMID 33778463, 2021). "While patients with T1D on intensive insulin therapy are at reduced risk for developing diabetic complications, the drawback is they experience a greater incidence of hypoglycaemia." (PMID 33855225, 2021). "Incretin therapy slows down gastric emptying, preserves insulin secretion (insulinotropic effects), suppresses glucagon secretion (glucagonostatic effects), and is associated with a much lower risk of hypoglycemia." (PMID 33802091, 2021). "In people with T1D, the increased hepatic glucose production can help override the insufficient change in glucagon:insulin ratio, thus reducing the risk of hypoglycemia during activity." (PMID 34444464, 2021). "Regarding MDI regimens, the use of modern ultra–long-acting insulin analogues along with carbohydrate counting help reduce the risk of hypoglycemia; patients on CSII therapy also have important tools to prevent this complication." (PMID 33905630, 2021).
Hypoglycemia (continued). "Potential contributors include inadequate coordination of insulin delivery and meal delivery, a common risk factor for hypoglycemia, as well as unfamiliarity with meal delivery protocols and hospital-specific protocols for administering insulin." (PMID 34336510, 2021). "Late-onset hypoglycemia presents an open problem and is caused by an elevated insulin sensitivity, where the timing of exercise in relation to meals plays a crucial role." (PMID 34489869, 2021). "Thirdly, hypoglycemia was the most frequent adverse event after MSCs treatment, which was associated with unadjusted exogenous insulin dosage." (PMID 33705413, 2021). "Our findings are contrary to most available literature, as, in the current meta-analysis, we found that patients with insulin glargine were associated with lower rates of hypoglycemia." (PMID 34345540, 2021). "Undoubtedly, the antihyperglycaemic therapeutic approach with the highest risk of hypoglycaemia is insulin therapy." (PMID 33532606, 2021). "GCK-HI patients are likely more at risk of hypoglycemia because the enzyme is costitutively activated for insulin secretion, while the carbohydrate intake is reduced under KD." (PMID 34635134, 2021). "The tendency to cause postprandial hypoglycemia is like subcutaneous therapy and more closely reflects physiological meal-induced insulin." (PMID 34540446, 2021). "Metformin administration results in controlling hyperglycemia comparable to insulin administration, but with a lower risk for iatrogenic hypoglycemia." (PMID 34502429, 2021). "Compared with once-daily basal insulin, once-daily IDegAsp showed similar overall hypoglycemia risk and significantly lower risk of nocturnal hypoglycemia." (PMID 34564455, 2021). "Treatment with insulin and several other insulin secretagogues can cause hypoglycemia, which remains a major limiting factor in achieving euglycemia in patients with type 1 diabetes (T1D) or T2D." (PMID 34752420, 2021). "Glucose control is aimed at measuring the patient’s need to adjust insulin dosage, or even to shut down insulin delivery in case of hypoglycemia (e.g. caused by exercise, miscalculated insulin bolus)." (PMID 32788632, 2020). "Type 2 diabetic patients often require intensive insulin treatment to maintain glycemic control, which leads to increased risk of hypoglycemia, weight gain, and further deterioration of INS resistance state." (PMID 32382087, 2020). "Patients who display higher glucose and cholesterol levels before intensive insulin therapy are at an increased risk of developing moderate hypoglycemia, and their insulin dosage should be adjusted particularly carefully." (PMID 32149152, 2020). "Most newly diagnosed patients still have sufficient insulin production to reduce risk of acute complications of T1D, such as hypoglycaemia, and long-term vascular complications." (PMID 32399500, 2020). "A prediction model established that the risk of hypoglycemia is directly proportional to increases in the total insulin dose until reaching a threshold of 0.8 units/kg where this relationship can no longer be observed." (PMID 32832557, 2020). "A meta-analysis of oral antidiabetic agents like insulin reported lowest risk of neonatal hypoglycemia with acarbose." (PMID 33403188, 2020). "By excluding studies which allow the use of therapies known to increase risk (ie, SU, insulin), we have aimed to improve the estimation of hypoglycaemia risk with newer AHA when used alone or in combination with each other compared to placebo." (PMID 31922027, 2020). "Those who were on a combination of insulin analogue and i.v.-administered insulin had a 50% increased risk of significant hypoglycaemia." (PMID 32300821, 2020). "DPP-4 inhibitors have been reported to stimulate insulin secretion and suppress glucagon secretion in a glucose-dependent way causing a low risk of hypoglycaemia and weight gain compared to other antidiabetic agents." (PMID 33126761, 2020).